CTLA4 (cytotoxic T-lymphocyte associated protein 4)
Diseases named in the same sentence as CTLA4 in open-access papers (continued):
Sharing a sentence is not in itself a finding about the gene and the disease.
lupus nephritis (7 papers, 2015 to 2024). Glomerulonephritis in the context of systemic lupus erythematosus. "Following genotype-mRNA expression, the analysis also showed the risk allele of rs17268364 was associated with low CTLA4 expression in lupus nephritis (LN) patients." (PMID 34736521, 2021). "The CTLA4 fusion protein (CTLA4Ig) has been reported to ameliorate lupus nephritis development in mice, while their phase I/II clinic trails have been underway in SLE patients." (PMID 31795353, 2019). "An additional murine model examined the effects of blocking CTLA-4′s costimulatory protein CD28, which led to the prevention of lupus nephritis development, prolonged animal survival, and reduced production of dsDNA antibodies." (PMID 38399467, 2024). "This is the single case of anti-CTLA-4 SLE in the literature and the only case of lupus nephritis identified." (PMID 38399467, 2024). "Except for CTLA4-Ig, no clinical trial on co-inhibitory targeted therapy for autoimmune vasculitis and lupus nephritis has been progressed until the middle of 2020." (PMID 33251233, 2020). "Nonetheless, a clinical trial study of CTLA4-Ig (Abatacept) and low dose cyclophosphamide combination therapy in patient with lupus nephritis has demonstrated a drug safety but was not effective to improve the clinical outcome of renal responses which may be due to the dose inadequacy of CTLA4-Ig." (PMID 31640263, 2019).
non-Hodgkin lymphoma (7 papers, 2011 to 2025). Distinct from Hodgkin lymphoma both morphologically and biologically, non-Hodgkin lymphoma (NHL) is characterized by the absence of Reed-Sternberg cells, can occur at any age, and usually presents as a localized or generalized lymphadenopathy associated with fever and weight loss. "An increase in T cells expressing ISMs—PD-1, TIM-3, CTLA-4 etc.—was detected in classical Hodgkin lymphoma (HL), several non-Hodgkin lymphomas (NHL) and MM5–8." (PMID 33257767, 2020). "However, the combination of anti-CTLA-4 and anti-PD-1 antibodies demonstrated a similar safety and efficacy profile compared to a previous report for anti-PD-1 monotherapy in Hodgkin lymphoma, non-Hodgkin lymphoma (NHL), and multiple myeloma." (PMID 30250823, 2018). "Although CTLA-4 is known as a negative regulator of T-cell proliferation, CTLA-4 expression was paradoxically detected on the malignant T-cells of patients with peripheral but not lymphoblastic or anaplastic Non-Hodgkin lymphomas (NHL)." (PMID 33384695, 2020).
Sjögren’s syndrome (7 papers, 2007 to 2025). "In order to study the affect of CTLA4 blockade on the sialadenitis and xerostomia associated with Sjögren's syndrome, CTLA4IgG was locally expressed in the salivary glands of C57BL/6.NOD-Aec1Aec2 mice, which develop a Sjögren's syndrome-like disease." (PMID 22369699, 2012). "This case-control study sought to investigate whether CTLA-4 CT60 and/or +49A/G polymorphisms were involved in the genetic predisposition to primary Sjögren syndrome (pSS)." (PMID 17341301, 2007). "The frequency of Sicca syndrome observed with the combination of anti-CTLA-4 antibody and anti-PD-1 antibody was 9.4%, and that with anti-CTLA-4 alone was 1.4%." (PMID 35159059, 2022).
testicular germ cell tumor (7 papers, 2019 to 2025). A germ cell tumor arising from the testis. "The results showed that in BLCA (P < 0.001), BRCA (P < 0.001), COAD (P < 0.05), and THCA (P < 0.001), PCSK9 was positively correlated with PDCD1, CD274, and CTLA4 but negatively correlated in HNSC (P < 0.05) and testicular germ cell tumor (TGCT) (P < 0.01)." (PMID 38600469, 2024). "So far, the expression of immune checkpoints, including CTLA-4 and PD-L1, has not been able to predict the response of germ cell tumor patients to immune checkpoint inhibitors." (PMID 39958339, 2025). "A study on testicular germ cell tumors (TGCTs) also showed high CTLA-4 expression in both seminoma and non-seminoma cases (seminoma: 87.2%; non-seminoma: 79.5%), a higher proportion than observed in our cohort." (PMID 39958339, 2025).
Thrombocytopenia (7 papers, 2020 to 2025). A reduction in the number of circulating thrombocytes. "In recent years, it had been shown that thrombocytopenia was associated with the transcription level of CTLA4 and regulation of T-cell activation." (PMID 35459882, 2022). "Moreover, we suggested that the rs11571315 might lead to thrombocytopenia via another pathway rather than affecting CTLA4 expression." (PMID 35459882, 2022).
viral hepatitis (7 papers, 2009 to 2022). An acute or chronic inflammation of the liver parenchyma caused by viruses. "Firstly, the results regarding associations between polymorphisms in CTLA-4/IL-18 and viral hepatitis were based on combining unadjusted findings of eligible studies due to the lack of raw data." (PMID 31801640, 2019). "So we call on scholars to examine associations between polymorphisms in CTLA-4/IL-18 and viral hepatitis in other populations." (PMID 31801640, 2019). "Fourth, we aimed to investigate associations between all polymorphisms in CTLA-4/IL-18 and viral hepatitis in the very beginning." (PMID 31801640, 2019). "In the past 20 years, results about associations between polymorphisms in CTLA-4/IL-18 and viral hepatitis were already reported by many association studies, yet the conclusions of these studies were still inconsistent." (PMID 31801640, 2019). "CTLA-4 rs231775 (recessive comparison: OR 1.33, 95% CI 1.23–1.43) polymorphism was found to be significantly associated with viral hepatitis in overall combined analyses." (PMID 31801640, 2019). "The aim of this study was to more comprehensively analyse associations between genetic polymorphisms in CTLA-4/IL-18 and viral hepatitis by combing the results of all relevant association studies." (PMID 31801640, 2019). "To better analyse associations between polymorphisms in CTLA-4/IL-18 and viral hepatitis, we carried out this study to get a more statistically reliable conclusion by combing the results of all relevant studies." (PMID 31801640, 2019). "In chronic viral hepatitis, immunosuppressive checkpoints, including PD-1/PD-L1, cytotoxic T-lymphocyte associated protein 4 (CTLA4), and T cell immunoglobulin and mucin domain 3 (TIM3), play an important role in immunosuppression by downregulating the T cell response." (PMID 35356200, 2022). "Fourteen eligible articles were about CTLA-4 polymorphisms and viral hepatitis." (PMID 31801640, 2019). "Secondly, the relationship between polymorphisms in CTLA-4/IL-18 and viral hepatitis may also be affected by environmental factors." (PMID 31801640, 2019). "The chronicity of viral hepatitis is associated with the persistent expression of PD-1 and CTLA-4." (PMID 28703774, 2017). "Thus, our meta-analysis may be statistically insufficient to observe the real underlying associations between polymorphisms in CTLA-4/IL-18 and viral hepatitis in certain groups." (PMID 31801640, 2019). "Immunosuppressive checkpoints, such as programmed death 1 (PD-1)/PD-L1, T cell immunoglobulin domain and mucin domain-3 (TIM-3), CTLA-4, play a significant role in immunosuppression in chronic viral hepatitis by suppressing T cell responses." (PMID 36685852, 2022). "Relationship of genetic polymorphisms in cytotoxic T-lymphocyte-associated antigen 4 (CTLA-4) and interleukin-18 (IL-18) with susceptibility to viral hepatitis was already investigated by many association studies." (PMID 31801640, 2019). "In acute viral hepatitis, PD-1 and CTLA-4 are up-regulated during the symptomatic phase, and then down-regulated after recovery." (PMID 28703774, 2017). "In the same study, we also investigated if T cells from patients with non-viral acute hepatitis present phenotypic changes in the expression of PD-1 or CTLA-4." (PMID 28703774, 2017). "There are few studies to investigate the phenotypic changes in the expression of PD-1 and CTLA-4 in acute viral hepatitis." (PMID 28703774, 2017). "This sub-population of immunoregulatory T cells suppresses the activation and effector function of CD4+ and CD8+ T cells; thus, activating Tregs by blocking CTLA-4 may further impair the ability of T cells to keep viral hepatitis suppressed." (PMID 25317333, 2014). "Nevertheless, the majority of eligible studies only focused on associations between polymorphisms in CTLA-4/IL-18 and viral hepatitis, so we could not explore genetic-environmental interactions in this meta-analysis." (PMID 31801640, 2019).
viral hepatitis (continued). "Viral hepatitis, including HAV, HBV, and HCV, was shown to have differential levels of PD-1 and CTLA-4 expression depending on disease progression." (PMID 28703774, 2017). "In viral hepatitis, HBV and HCV persist with functionally-impaired, virus-specific peripheral T cells as well as intrahepatic T cells that over-express PD-1 and CTLA-4." (PMID 28703774, 2017).
acute graft versus host disease (6 papers, 2014 to 2024). A syndrome of immunologically mediated tissue damage that may occur following an allogeneic transplant, usually affecting the skin, liver, and GI tract. "Also, the same group has shown that donor and recipient CTLA-4 mRNA and recipient membrane protein expression measured before transplantation are prognostic for acute GVHD." (PMID 36817455, 2023). "In acute graft-versus-host disease (GVHD), both human and murine experimental evidence demonstrates that co-blockade using tetravalent CTLA-4-Ig and LAG-3-Ig could synergistically suppress T cell responses, prevent acute GVHD, and decrease GVHD fatality rates as well." (PMID 30603054, 2018).
Behçet's disease (6 papers, 2012 to 2024). "Therefore, the expression of miR-155 is elevated in Behcet's disease and is associated with the upregulation of TNF-α and downregulation of CTLA-4 genes." (PMID 38462628, 2024). "The presence of anti-CTLA-4 antibody has been reported in a fraction of Behçet's disease patients that might be possibly involved in abnormal T-cell responses." (PMID 24991555, 2014). "Behcet's disease is characterized by a notable increase in the expression of both miR-155 and TNF-α, while the expression of CTLA-4 is significantly reduced." (PMID 38462628, 2024). "Whereas the roles of costimulation molecules have not been fully explored in Behçet's disease, the presence of anti-CTLA-4 antibody has been reported in a fraction of Behçet's disease patients." (PMID 21977335, 2012).
bladder tumor (6 papers, 2016 to 2024). "We repeated this experiment initiating treatment with anti-CTLA4 when MB49 bladder tumors reached a tumor volume of approximately 100 to 200 mm3." (PMID 38330013, 2024). "elucidated the underlying tumor rejection mechanisms for the combination therapy of PD-1 with CTLA-4 inhibitors by performing a detailed analysis of human bladder tumor samples together with murine MB49 bladder tumor model." (PMID 33585182, 2020). "Clearly, these results point to synergistic effects of α-CTLA-4 and α-PD-1 in eliminating bladder tumours." (PMID 27498556, 2016). "While TILs from human bladder tumour predominantly co-expressed CTLA-4 and PD-1, 25% of TILs from murine MB49 tumours co-expressed CTLA-4 and PD-1 with additional 36 and 4% expressing either PD-1 or CTLA-4 alone." (PMID 27498556, 2016). "To determine whether Ephx2 gene induction was specific to ICI targeting PD-1, we utilized C57BL/6 mice inoculated with 1 × 106 MB49 bladder tumor cells which were randomized to receive treatment with systemic anti-CTLA-4 or vehicle." (PMID 38330013, 2024). "We then assessed how α-CTLA-4 impacts the PD-1/PD-L1 pathway in human and murine bladder tumours." (PMID 27498556, 2016). "Here, we provide direct evidence that PD-1 is a primary suppressive pathway utilized by bladder tumour cells to ‘escape' α-CTLA-4 monotherapy by showing that α-CTLA-4 therapy upregulates PD-1/PD-L1 expression and that bladder tumour cells express high levels of PD-L1." (PMID 27498556, 2016). "To examine if the PD-1/PD-L1 pathway can be attributed to the low efficiency of α-CTLA-4 monotherapy, we analyzed PD-1 and CTLA-4 expression on TILs isolated from human and murine bladder tumours." (PMID 27498556, 2016). "Our results indicate neither α-CTLA-4 nor α-PD-1 affects distribution of NK and NKT cells in MB49 bladder tumours." (PMID 27498556, 2016).
choriocarcinoma (6 papers, 2019 to 2025). An aggressive malignant tumor arising from trophoblastic cells. "Infiltrating immune cells of all histological subtypes expressed PD-L1 and CTLA-4 while in tumor cells CTLA-4 expression was higher in yolk sac tumor, choriocarcinoma, and teratoma samples." (PMID 35756636, 2022). "CTLA-4 TC intensity was significantly higher in yolk sac tumor, choriocarcinoma and teratoma, while PD-L1 TC positivity was significantly more frequent in choriocarcinoma." (PMID 31614500, 2019).
cutaneous squamous cell carcinoma (6 papers, 2020 to 2025). "In contrast, in cutaneous squamous cell carcinoma, CD80 which is highly expressed by tumor cells has been shown to mediate cancer cell proliferation, T-cell suppression, and failure through contact with CTLA4." (PMID 36892747, 2023).
eosinophilia (6 papers, 2019 to 2026). "Regarding other diagnostic criteria, peripheral eosinophilia concomitant with the rash appearance has been reported for both PD-1/PD-L1 and CTLA-4 inhibitors." (PMID 37370736, 2023). "Blockade of CTLA-4 promotes allergic responses with eosinophilia and elevated IgE levels, while increased CTLA-4 inhibits allergic inflammation." (PMID 41596548, 2026). "This novel finding is in line with reports that the development of blood eosinophilia upon treatment with immunotherapy drugs, such as checkpoint inhibitors anti-CTLA-4 and anti-PD-1, is a predictor of the clinical response." (PMID 32121531, 2020). "Blockade of CTLA-4 maintains or increases allergic responses with eosinophilia and elevated IgE levels, while increased CTLA-4 inhibits allergic inflammation." (PMID 31139837, 2019).
fibrosis (6 papers, 2017 to 2025). the formation of excess fibrous connective tissue in an organ or tissue in a reparative or reactive process. "Mice initially infected with female S. mansoni cercariae displayed smaller hepatic granulomas, livers and spleens, less hepatic fibrosis and higher expression of Ctla4." (PMID 28542175, 2017). "Ex vivo activation of isolated CTLA4-expressing CD8+ cells from mice with established fibrosis resulted in enhanced cytolysis of senescent cells, suggesting that impaired immune-mediated clearance of these cells contributes to persistence of lung fibrosis in this murine model." (PMID 40100323, 2025). "Blocking CTLA4 in immune cells may help regenerate lungs and reduce fibrosis in idiopathic pulmonary fibrosis." (PMID 40100323, 2025).
gastroesophageal junction adenocarcinoma (6 papers, 2023 to 2025). A carcinoma that arises from glandular epithelial cells of the esophagogastric junction. "In a phase 1b/2 study, combining cadonilimab, a bispecific antibody targeting PD-1 and CTLA-4, with chemotherapy showed promising efficacy in gastroesophageal junction adenocarcinoma, with an objective response rate of 52.1%." (PMID 38898505, 2024).
laryngeal carcinoma (6 papers, 2017 to 2025). Carcinoma that arises from the laryngeal epithelium. "Immune checkpoint molecules have become significant diagnostic and therapeutic targets in laryngeal cancer, with PD-L1 (Programmed Death-Ligand 1) and CTLA-4 (Cytotoxic T-Lymphocyte Associated Protein 4) being the most prominent examples." (PMID 39452555, 2024). "Although CTLA-4 inhibition has demonstrated potential in other forms of cancer, its function as a biomarker for laryngeal cancer is still unclear." (PMID 39452555, 2024). "We found that laryngeal cancer samples in the low-risk score group were more sensitive to PDCD1, LAG3, CTLA4, and TIGHT." (PMID 36335208, 2022). "Certain markers were associated with tumor localization: CD57 higher density was seen in oropharyngeal tumors (p=0.0007), CD4 lower density was seen in laryngeal tumors (p=0.03) and lower CTLA4 tumor cell expression in laryngeal carcinomas (p=0.04)." (PMID 28038471, 2017). "Beyond these approved agents, several ICIs are under investigation for laryngeal cancer, including dostarlimab (anti-PD-1), ipilimumab and tremelimumab (anti-CTLA-4), atezolizumab and durvalumab (anti-PD-L1), and lirilumab (anti-killer cell immunoglobulin-like receptor)." (PMID 40061133, 2025). "This review examines the role of ICIs in laryngeal cancer management, with a focus on pembrolizumab and nivolumab (anti-PD-1 agents), which are clinically established, as well as investigational therapies such as dostarlimab (anti-PD-1), atezolizumab (anti-PD-L1), and ipilimumab (anti-CTLA-4)." (PMID 40061133, 2025). "We found that low-risk laryngeal cancer samples were more sensitive to PDCD1, LAG3, CTLA4, and TIGHT, indicating that fatty acid metabolism is of interest in terms of assessing the TME characteristics in patients with laryngeal cancer." (PMID 36335208, 2022). "Compared to PD-L1, CTLA-4, another immune checkpoint molecule, has not been as thoroughly researched in laryngeal cancer cases." (PMID 39452555, 2024).
leiomyosarcoma (6 papers, 2018 to 2023). An uncommon, aggressive malignant smooth muscle neoplasm, usually occurring in post-menopausal women. "Newly identified pathways include FGFR signaling and CTLA4 inhibitory signaling and represent potential targets for treatment of subgroups of leiomyosarcoma patients." (PMID 37492373, 2023). "The majority of the of the positive reactions were detected in the cases with leiomyosarcoma (Groups II-IV); PD-L1 in 18 (40%), CTLA-4 in 4 (9%), and IDO in 6 (13%) cases." (PMID 36104728, 2022). "Moreover, 9% and 13% of leiomyosarcomas express CTLA-4 and IDO proteins, respectively." (PMID 36104728, 2022). "PORCUPINE identified 37 heterogeneously regulated pathways, including pathways representing potential targets for treatment of subgroups of leiomyosarcoma patients, such as FGFR and CTLA4 inhibitory signaling." (PMID 37492373, 2023). "As expected, increased expression of IDO1, CTLA4, and PDL1 was observed in Oncopig leiomyosarcoma tumors relative to control muscle samples." (PMID 29930558, 2018). "Among the detected pathways, we identified pathways that could represent potential targets for treatment of subgroups of leiomyosarcoma patients, including RB1/E2F1 signaling, pathways involved in FGFR signaling, and CTLA4 inhibitory signaling." (PMID 37492373, 2023). "Notably, in leiomyosarcoma, TJP1 knockdown led to the activation of multiple signaling pathways, including the NF-κB pathway and growth factor receptor signaling, resulting in enhanced tumor growth because of CSF1 and CTLA4 expression." (PMID 37790849, 2023).